IGKV1D-13 (immunoglobulin kappa variable 1D-13)
Description:
V region of the variable domain of immunoglobulin light chains that participates in the antigen recognition. Immunoglobulins, also known as antibodies, are membrane-bound or secreted glycoproteins produced by B lymphocytes. In the recognition phase of humoral immunity, the membrane-bound immunoglobulins serve as receptors which, upon binding of a specific antigen, trigger the clonal expansion and differentiation of B lymphocytes into immunoglobulins-secreting plasma cells. Secreted immunoglobulins mediate the effector phase of humoral immunity, which results in the elimination of bound antigens. The antigen binding site is formed by the variable domain of one heavy chain, together with that of its associated light chain. Thus, each immunoglobulin has two antigen binding sites with remarkable affinity for a particular antigen. The variable domains are assembled by a process called V-(D)-J rearrangement and can then be subjected to somatic hypermutations which, after exposure to antigen and selection, allow affinity maturation for a particular antigen.
Synonyms: IGKV1D13; L18
Gene: Immunoglobulin variable (V) gene on chromosome 2 (90,154,073 to 90,154,574, forward strand). Ensembl gene ENSG00000276566.
Subcellular location: Secreted; Cell membrane
Gene Ontology:
Biological process: immune response
Cellular component: extracellular region; immunoglobulin complex; plasma membrane
Homologues: Orthologues: chimpanzee IGKV1D-13 (83% identical), mouse Igkv15-103 (74% identical). Paralogues in human: IGKV1-9 (93% identical), IGKV1-12 (91% identical), IGKV1-39 (91% identical), IGKV1-5 (91% identical), IGKV1-6 (91% identical), IGKV1D-12 (91% identical), IGKV1D-16 (91% identical), IGKV1D-39 (91% identical), IGKV1-16 (89% identical), IGKV1-17 (89% identical), IGKV1-27 (88% identical), IGKV1-8 (88% identical), and 81 more.
Diseases named in the same sentence as IGKV1D-13 in open-access papers:
IGKV1D-13 is named in the same sentence as 2 diseases in open-access papers, as found by Europe PMC text mining. Sharing a sentence is not in itself a finding about the gene and the disease. The quoted sentences say what the papers report.
Obesity (1 paper, 2024). Accumulation of substantial excess body fat. "The top-altered proteins in our study include VPS13C, ADIPOQ, and IGKV1D-13 which can be used as biomarkers for obesity-related IR and to identify individuals with a future risk for T2D." (PMID 38672154, 2024).
IGKV1D-13 also shares sentences with these, for which no sentence is quoted: Hepatic steatosis (1 paper).